IL6 (interleukin 6)
Diseases named in the same sentence as IL6 in open-access papers (continued):
Sharing a sentence is not in itself a finding about the gene and the disease.
colitis (continued). "The TNBS mice that received cellulose gel with CNP-miR146a on day two showed reduced IL-6 expression in their colons compared to the untreated TNBS colitis mice (p = 0.032) and were not significantly different from the controls." (PMID 38786849, 2024). "IL-6-induced signal transducer and activator of transcription 3 (STAT3) signaling plays a key role in the differentiation of CD4+ T cells to Tregs or Th17 cells, which determines the quiescence or the development of colonic inflammation." (PMID 38257292, 2024). "In PBS-treated males, colitis resulted in markedly elevated IL-6 and no significant changes in PST, IL-22, and IL-18 levels compared to in the corresponding non-colitic PBS-treated mice." (PMID 39684467, 2024). "Similarly, oral administration of another AhR agonist, β-naphthoflavone, was shown to decrease the severity of DSS-induced colitis while reducing pro-inflammatory cytokines such as tumor necrosis factor -α (TNF-α), IL-6, and IL-1β." (PMID 39767818, 2024). "The results show that CA effectively alleviated colitis, as evidenced by an increased colon length, lowered disease activity index (DAI) and histological scores, and decreased tumor necrosis factor-α (TNF-α) and interleukin-6 (IL-6) expression levels." (PMID 38255916, 2024). "Interestingly, when we treated the infected colitis mice with LGG or BL, we observed a significant increase in IL-6, CXCL2, IL-1β, TNF-α, IL-17a, and IL-22 gene expression in the cecal tissue, indicating an enhanced inflammatory response." (PMID 38397855, 2024). "Daidzein inhibited the expression of IL-6 and IL-1β in mice with DSS-induced colitis." (PMID 39318778, 2024). "The levels of interleukin-6 (IL-6) and tumor necrosis factor-α (TNF-α) in the serum were measured to investigate the ability of the selected CFSs to reduce the level of pro-inflammatory cytokines in mice with DSS-induced colitis." (PMID 38674829, 2024). "Also, these compounds possess anti-inflammatory properties, suppressing inflammatory pathways involved in colitis and inhibiting the NLRP3 inflammasome, thereby reducing pro-inflammatory cytokines like IL-1β, IL-6, and TNF-α." (PMID 39061864, 2024). "The results revealed significant IL‐1β, IL‐6, and TNF‐α pro‐inflammatory cytokine up‐regulation in the UC model group (p < 0.05), suggesting the presence of an inflammatory response in the mice with colitis." (PMID 38334213, 2024). "Additionally, both limonene and terpineol demonstrate anti-inflammatory effects by decreasing the levels of pro-inflammatory cytokines such as TNF, IL-6, leptin, and AOPP in a colitis induction model." (PMID 39456515, 2024). "However, the KO of HTR2B in the intestinal epithelial cells of mice aggravates the severity of AOM/DSS-induced colitis by inhibiting TGF-β/SMAD signaling and activating IL-6/STAT3 signaling." (PMID 39180723, 2024). "In addition, the graph illustrates the significant reductions in the IL‐1β, IL‐6, and TNF‐α expression levels following BLF administration, further supporting the anti‐inflammatory effect of BLF in AD mice with colitis." (PMID 38334213, 2024). "Secondly, B. bifidum has immune-regulatory functions, inhibiting the expression of inflammatory factors interleukin (IL)-1β, tumor necrosis factor (TNF)-α, IL-6, and interferon (IFN)-γ, while promoting IL-10 expression, thus facilitating gut damage repair in colitis mice." (PMID 39525506, 2024). "Also, sinapic acid reduces serum levels of proinflammatory cytokines (TNF-α, IL-1β, IL-6, IL-17α, IL-18, and interferon (IFN)-γ) and increases anti-inflammatory cytokines (IL-4 and IL-10) in Kunming mice with DSS-induced colitis." (PMID 38732594, 2024). "Additionally, hydroxytyrosol has been shown to lower levels of IL-1β, IL-6, and TNF-α and increase the level of the anti-inflammatory cytokine IL-10 to ameliorate intestinal inflammation in mice colitis models." (PMID 38891778, 2024).
colitis (continued). "Among the various Th-cell subsets, activation of the Th1/Th17-cell response, characterized by a cytokine profile featuring components such as TNF-α, IFN-γ, interleukin (IL)-6, and IL-17, also contributes to the development of the acute phase of DSS-induced colitis." (PMID 39176394, 2024). "Cytokines are important mediators of inflammation and elevated levels of major proinflammatory cytokines such as tumor necrosis factor (TNF), interleukin (IL)-6, IL-1β, and interferon-gamma (IFN-γ) are observed in patients with ulcerative colitis and also in chemically induced colitis models." (PMID 38998493, 2024). "Besides, 3-MA increased the proinflammatory factors levels (TNF-α, IL-6, IFN-γ, IL-22) in ANI/NEO-treated mice with DSS-induced colitis." (PMID 38354108, 2024). "SNS significantly reduced colonic inflammation, similar to the effects of vagus nerve stimulation (VNS), by modulating autonomic function and cytokine production (decreased TNF-α, IL-6, and IL-17A, increased IL-10), indicating potential therapeutic utility for IBD treatment." (PMID 39605787, 2024). "They found that the polysaccharide could suppress clinical manifestations of colitis by down-regulating the markers of oxidative stress such as nitric oxide (NO) and the pro-inflammatory cytokines, including IL-1β, TNF-α, and IL-6." (PMID 38257292, 2024). "The results showed ZW3 partially mitigated body weight loss, disease activity index (DAI), colon shortening, and suppressed immune response in colitis mice, as evidenced by the reduction in the levels of the inflammatory markers IL-1β, TNF-α, and IL-6 (p < 0.05)." (PMID 38203732, 2024). "Suppress colitis-stimulated tissue oxidative stress.Suppress TNF-α, IL-6, IL-1β, and IL-33." (PMID 38585461, 2024). "Similar results were obtained in DSS-induced colitis mice, as 4-methyl-esculetin administered orally at 25 mg/kg daily, improved microscopic parameters, reduced MPO activity, lowered colonic IL-6 levels, and prevented GSH depletion compared to the DSS-control group 562." (PMID 39494333, 2024). "The qRT‐PCR results demonstrated significantly elevated levels of pro‐inflammatory factors (IL‐6 and TNFα) in colons of the colitis animal model, while no significant change in the levels of anti‐inflammatory cytokines (IL‐10) was observed." (PMID 38340032, 2024). "In addition, only CD11b+CD103- DCs secreted IL-6, IL-12p40, and IL-23p19 from the mLN of DSS-colitis mice, which was further enhanced by the treatment with FimH." (PMID 38077339, 2023). "In addition, other research has proved that AG ameliorates colitis in DSS-induced colitis mice and HCT-116 and HT-29 cells by alleviating the shortening of the colon and suppressing inflammation by down-regulating the expression of TNF-α, IL-6, and IL-8." (PMID 37920216, 2023). "JARID2, another downstream target of miR-155, has been shown to suppress the expression of Est-1, a negative modulator of Th17 cells in DSS-induced colitis, and promote the expression of IL-6, IL-17, and IL-23, as well as the maturation of Th17 cells." (PMID 36768556, 2023). "Oral QT-loaded silk fibroin nanoparticles (QSFN) can produce obvious intestinal anti-inflammatory properties by down regulating proinflammatory cytokines (TNF-α, IL-1β, IL-6, MCP-1, ICAM-1, NLRP3, iNOS) and significantly reducing the DAI score of DSS-induced colitis mice." (PMID 37033644, 2023). "Colonic levels of myeloperoxidase, IL-6, and TNF-α decreased significantly in rats treated with the mixture, while a significant decrease in (Toll-like receptor) TLR-4 mucosal gene expression and a significant improvement in colitis were observed." (PMID 37569412, 2023). "Furthermore, activation of FXR has been shown to restrict the expression of inflammatory cytokines such as IL-1β and IL-6, and chemokines such as CCL2 in mouse colitis models and human CD14+ monocytes and DCs in vitro." (PMID 38169949, 2023).
colitis (continued). "It is thus possible that the inflammatory response during colitis-induced FGF21 expression inhibits intestinal HIF1α expression, leading to a decrease in IL-22 and therefore exacerbating the expression of inflammatory IL-6 production." (PMID 37432218, 2023). "Also, stimulation of canine MSCs with TNFα elevates TSG-6 and PGE2 resulting in in vivo benefit by regulating colonic inflammatory cytokines such as IL1β, IL6, and IL10, and ameliorating induced colitis in mice." (PMID 37275605, 2023). "Our data show the participation of other cytokines besides IL-6, such as G-CSF, MCP-1, IL1β, and IL10, which are upregulated during DSS-induced colitis in the susceptible AIRmin SS and not in the resistant AIRmin RR mice." (PMID 36792680, 2023). "Additionally, after the occurrence of colitis, proinflammatory cytokines, such as TNF-α, IL-6 and IL-1β, are secreted and accumulated in large quantities due to the excessive activation of immune cells." (PMID 36902109, 2023). "In addition, the levels of oxidative stress (MPO, SOD, and MDA) and inflammatory cytokines (TNF-α, IL-1β, IL-6, and IL-10) were reversed by PHI in colitis mice." (PMID 36768559, 2023). "There is also a general increase in Il6 in DSS colitis in male animals in the therapeutic trial." (PMID 37047397, 2023). "We also found increased expression of IL-6 and STAT3 signaling in Cldn3KO mice with colitis." (PMID 38010872, 2023). "Additionally, the brown seaweed extract reduced IL-6, IL-8, and TNF-α expressions in piglets with LPS-induced colitis, thereby inhibiting the pro-inflammatory factor response." (PMID 37233678, 2023). "In patients with extensive colitis, the AUC of CRP, FC, IL-6, FDP, GSP and α1-MG independently predicted MES 3 is 0.70, 0.65, 0.70, 0.73, 0.76, and 0.70, respectively, and the AUC of IL-6 + GSP+ α1-MG predicted MES3 can reach 0.82, with sensitivity and specificity of 66% and 94%, respectively." (PMID 37457023, 2023). "In our study, L. sakei CVL-001 administration led to decreased gene expression levels of pro-inflammatory cytokines, such as IL-1β, TNF-α, and IL-6, and increased gene expression levels of anti-inflammatory cytokines, such as IL-10, against DSS-induced colitis." (PMID 37317332, 2023). "We tested the genetic expression of inflammatory cytokines and found that the LCP diet reduced their expression in colitis, particularly in the P10 group, wherein levels of TNF-α, IL-1β, and IL-6 were diminished 3.0-, 3.2-, and 2.1-fold compared to the M group." (PMID 37761037, 2023). "Abnormal immune responses in the gut are a feature of colitis, which is characterized by the increase of inflammatory cytokines (TNF-α, IL-1β, IL-6, etc) and decrease of anti-inflammatory cytokines, such as IL-10, and these changes are observed in patients with IBD and DSS-induced colitis mice." (PMID 37297494, 2023). "In patients with IBD, STAT3 is activated by IL-6 as well as other cytokines and factors in the microenvironment; IL-11, IL-22, HGF, and EGF family members are active during the colitis stage, and may also be active during CAC/CRC tumorigenesis." (PMID 38002302, 2023). "Ruminiclostridium-6 could contribute to the release of proinflammatory factors such as IL-6, IL-1β, TNF-α and IL-8 and deteriorate colitis." (PMID 37679821, 2023). "Finally, the mouse model of colitis was established and SOD, MDA, TNF-α, IL-1β, IL-6 and P38 as well as ERK were detected from mice." (PMID 38024351, 2023). "The NF-κB/IL-6/Stat3 and JAK2/Stat3 pathways may be critically involved in CAC tumorigenesis, and it was found that AFE ameliorated colitis and inhibited CAC by downregulating these two inflammation-related signaling pathways." (PMID 38004214, 2023). "Consistently with the data obtained in murine colitis, Ade/HA determined a significant decrease in the release of IL-1β, TNF-α, IL-6, MPO, and MDA accumulation in cytomix-stimulated tissues, and these effects were accompanied by a significant reduction in the expression of HYAL-1." (PMID 38203336, 2023).
colitis (continued). "Our study showed that the newly isolated C4 strain could effectively reduce the expression levels of IL-1β, IL-6, and TNF-α, and upregulate the expression levels of ZO-1 and occludin to alleviate the symptoms in DSS-induced colitis mice." (PMID 37152759, 2023). "In order to confirm whether HeHi_Lp administration also affects the gene expression of inflammatory cytokines, the mRNA expression of TNF-α, IL-6, and IL-1 was measured in the colon tissue of mice with DSS-induced colitis using real-time PCR." (PMID 37891901, 2023). "In colitis mouse models, bile acids can effectively limit M1 macrophages to secret proinflammatory cytokines such as TNF-α, IFN-γ, IL-6, and IL-12, and increase the binding of macrophages to IL-10 gene promoter and differentiation into IL-10 secreting M2 macrophages." (PMID 38169949, 2023). "At present, DPP-4 inhibitors are used to treat experimental mice colitis (DSS-induced mice colitis and TNBS-induced mice colitis), and their mechanism may be inhibiting IL-6 and TNF-α." (PMID 37554552, 2023). "Furthermore, PELNs demonstrated the ability to suppress the expression of pro-inflammatory cytokines (IL-6, IL-12, IL-1β, and TNF-α) and MPO, and increase the levels of the anti-inflammatory cytokine IL-10, thereby alleviating DSS-induced colitis in mice." (PMID 37653406, 2023). "Other studies report that resveratrol reduces inflammation in patients with UC to improve their quality of life and disease clinical colitis activity, and in animal models of IBD, where there are reduced pro-inflammatory markers (TNF-α, IFN-γ, IL-1β, IL-6, and IL-4) and DAI." (PMID 37660064, 2023). "However, the protective effects of FGF21 KO against DSS-induced colitis and the colonic phosphorylation of STAT3 cannot be explained by the IL-6 regulation since IL-6 expression was reduced in the KO mice." (PMID 37432218, 2023). "Subsequently, we further analyzed the level of inflammatory factors in colon tissue and found that the pro-inflammatory cytokines IL-1β, IL-6, IL-12, IL-17 and TNF-α were increased and the anti-inflammatory cytokine IL-10 was decreased in the colon of DSS-induced colitis." (PMID 37438752, 2023). "Therefore, we assessed the serum level of cytokines at the end of our colitis experiments, and found that IFN-γ, TNF, IL-2, IL-6, and IL-17 levels were all much higher in DSS-induced colitis mice than in control mice." (PMID 37275854, 2023). "In addition, VAWE recovers the mucosal barrier function of colitis, and protects against cell infection by down‐regulation of pro‐inflammatory cytokines (TNF‐α and IL‐6) and reduction of phagocytosis." (PMID 36596647, 2023). "TNBS-induced colitis rats showed significantly increased serum levels of TNF-α, IL-2, and IL-6." (PMID 35239781, 2022). "Besides, nanostructured lipid carrier-oleuropein was tested in the DSS-induced colitis experimental model and it exhibited a modulation of the inflammatory biomarkers via decreasing the level of TNF-α, IL-6, and hindering neutrophil infiltration." (PMID 35990343, 2022). "Also, G. lucidum ethanol extract administration decreased the expression of inflammatory mediators IL-1β, IL-6, IL-17, and TNF-α in DSS-induced colitis." (PMID 36553765, 2022). "Han and colleagues reported that atractylenolide III (5, 10 mg/kg) could ameliorate DSS-induced colitis inflammatory and oxidative stress by regulating the MDA and GSH contents, SOD activity, and the expression of TNF-α, IL-6, COX-2, and iNOS mRNA." (PMID 36160392, 2022). "Furthermore, the levels of inflammatory mediators and cytokines, including TNF-α, IL-1β, and IL-6, were significantly lower in the BCP group than those in the untreated DSS-induced colitis group." (PMID 36431883, 2022). "The elevated levels of IL-1α, IL-1β, IL-3, IL-6, IL-9, IL-12 (P40), IL-12 (P70), IL-17, GM-CSF, and G-CSF in response to DSS treatment in the current study, supports the strong involvement of macrophage activation in the DSS induced colitis model." (PMID 36365201, 2022).
colitis (continued). "The relationship between variables related to colitis and the core microbiota communities in the PHE group demonstrated that the abundance of Akkermansia was negatively related to the expression of PGE2, IL-6, and IL-1β." (PMID 36569313, 2022). "The results showed that compared to DSS-induced colitis mice, 300 mg/kg PD increased the level of IL-6 but did not significantly alter other cytokine levels in colonic tissues." (PMID 35933374, 2022). "Also, in other studies, serum TNF-α level was decreased in obese mice fed a high-fat diet supplemented with RB compared to obese mice, and γ-oryzanol significantly reduced the up-regulated expression of IL-1β, IL-6, TNF-α, and COX-2 mRNA in mice with colitis." (PMID 34636986, 2022). "A study reported that glycyrrhetic acid (10, 50 mg/kg) could decrease the levels of IL-6, IL-1β, and TNF-α, and suppress the expression of COX-2, NF-κB, and PGE2 protein for treating the DSS-induced colitis mice." (PMID 36160392, 2022). "In the present study, colonic expressions of IL-1β and IL-6, major macrophage-related proinflammatory cytokines relevant to IBD, were still exacerbated in mPGES-1−/− mice under the CD4+ T cell depletion during colitis." (PMID 34983695, 2022). "In the present study, except for the obvious UC symptoms, we observed an increase in pro-inflammatory cytokines (TNF-α, IL-6) and MPO activity as well as a decrease in anti-inflammatory cytokines such as IL-10, which are closely related to the severity of colitis." (PMID 36295859, 2022). "We show that BBR suppresses the activation of macrophages and granulocytes in colitis mouse models, accompanied by decreases in the production of inflammatory cytokines including IL1β, TNFα, and IL6, yet, T cells are not significantly affected." (PMID 36528592, 2022). "Additionally, Fuc-S also successfully prevented colitis by inhibiting the production of TNF-α, IFN-γ, IL-6, and IL-17A in the colons of colitic mice." (PMID 36662189, 2022). "By contrast, the expression of Il1β, Ifng, and TNF-α (Tnf) was significantly decreased by L. reuteri treatment during DSS-induced colitis (p < 0.05) without affecting Il6 or Il10 levels (p > 0.05)." (PMID 35320932, 2022). "The treatment was tested during and after colitis induction and the results showed that early treatment (days 0 and 3) attenuated acute colitis, with significantly lower concentrations of inflammatory cytokines (TNF-α and IL-6) in the colonic mucosa, compared to untreated animals." (PMID 35939430, 2022). "Furthermore, ISL can protect mouse gastrointestinal tracts, and suppress DSS/AOM-induced colon inflammation-related tumorigenesis by down regulating PGE2 and IL-6." (PMID 36278232, 2022). "Similarly, less pronounced activation of the NF-κβ signaling pathway and decreased expression of inflammatory cytokines, including IL-1β, IL-6, MCP1, and CCL3 were observed in the colon of KO to WT compared to WT chimera mice with DSS colitis." (PMID 35743072, 2022). "Compared to acute DSS-induced colitis, chronic DSS paradigms lead to a switch of serum immunophenotype towards a more Th2-like pattern with increased levels of Il-4 and Il-10, while levels of Ifn-γ and Il-6 remain elevated." (PMID 36232412, 2022). "Trim27 deficiency could decrease the levels of pro-inflammatory cytokines (IL-6, TNF-α, and IL-17A) in the colonic mucosa and suppress the DSS-induced colitis." (PMID 35565775, 2022). "In vivo overexpression of the Rasgrp1 3’ untranslated region enhances lipopolysaccharide-induced systemic inflammation and dextran sulphate sodium-induced colitis in Il6+/+ mice but not in Il6-/- mice." (PMID 36385095, 2022). "Baicalin ameliorated TNBS-induced colitis injury by suppressing TLR4 signaling in a concentration-dependent manner, inhibiting NF-κB activation and limiting the inflammatory response, such as ICAM-1, MCP-1, Cox-2, TNF-α, IL-1β and IL-6." (PMID 35484567, 2022).